BRD4 (bromodomain containing 4)
Description:
Chromatin reader protein that recognizes and binds acetylated histones and plays a key role in transmission of epigenetic memory across cell divisions and transcription regulation. Remains associated with acetylated chromatin throughout the entire cell cycle and provides epigenetic memory for postmitotic G1 gene transcription by preserving acetylated chromatin status and maintaining high-order chromatin structure. During interphase, plays a key role in regulating the transcription of signal-inducible genes by associating with the P-TEFb complex and recruiting it to promoters. Also recruits P-TEFb complex to distal enhancers, so called anti-pause enhancers in collaboration with JMJD6. BRD4 and JMJD6 are required to form the transcriptionally active P-TEFb complex by displacing negative regulators such as HEXIM1 and 7SKsnRNA complex from P-TEFb, thereby transforming it into an active form that can then phosphorylate the C-terminal domain (CTD) of RNA polymerase II. Regulates differentiation of naive CD4(+) T-cells into T-helper Th17 by promoting recruitment of P-TEFb to promoters (By similarity). Promotes phosphorylation of 'Ser-2' of the C-terminal domain (CTD) of RNA polymerase II. According to a report, directly acts as an atypical protein kinase and mediates phosphorylation of 'Ser-2' of the C-terminal domain (CTD) of RNA polymerase II; these data however need additional evidences in vivo. [Isoform B]: Acts as a chromatin insulator in the DNA damage response pathway. Inhibits DNA damage response signaling by recruiting the condensin-2 complex to acetylated histones, leading to chromatin structure remodeling, insulating the region from DNA damage response by limiting spreading of histone H2AX/H2A.x phosphorylation.
Synonyms: HUNK1; HUNKI; MCAP; CAP; FSHRG4; CDLS6
Tractability: Small molecule: a drug acting on it is in phase 2 or 3 trials; a structure with a bound ligand is known; a high-quality ligand is known; it has a binding pocket of medium quality; it belongs to a druggable protein family. PROTAC: it is named in the literature on targeted protein degradation; UniProt records ubiquitination sites on it; ubiquitination databases record sites on it; its protein half-life has been measured; a small molecule that binds it is known.
Target class: Epigenetic regulator; Bromodomain; Reader
Chemical probes: (+)-JQ1 (high quality), A1874 (high quality), ABBV-744 (high quality), AZD-5153 (high quality), BI 894999 (high quality), BRD4 degrader AT1 (high quality), GSK046 (high quality), GSK620 (high quality), GSK789 (high quality), GSK973 (high quality), I-BET151 (high quality), MS436 (high quality), MT1 (high quality), MZ1 (high quality), MZP-54 (high quality), PD134703, PD134704, PFI-1 (high quality), Pelabresib anhydrous (high quality), biBET (high quality), and 3 more
Safety:
Unwanted effects reported when the protein is acted on. In parentheses: how it was acted on, where the effect was seen, and who reports it.
Gastrointestinal toxicity observed in rats (inhibition; gastrointestinal; source: Brennan et al. (2024))
Gene: Protein-coding gene on chromosome 19 (15,235,519 to 15,332,545, reverse strand). Ensembl gene ENSG00000141867.
Subcellular location: Nucleus; Chromosome; Chromosome (Isoform B)
Subcellular location (Human Protein Atlas): Nucleoplasm; Mitotic chromosome
Pathways (Reactome):
Disease: Potential therapeutics for SARS
Immune System: Regulation of PD-L1(CD274) transcription
Gene Ontology:
Molecular function: chromatin binding; enzyme binding; histone H3K27ac reader activity; histone H3K9ac reader activity; histone H4 reader activity; histone H4K12ac reader activity; histone H4K16ac reader activity; histone H4K5ac reader activity; histone H4K8ac reader activity; P-TEFb complex binding; protein binding; RNA polymerase II C-terminal domain binding; RNA polymerase II CTD heptapeptide repeat kinase activity; transcription cis-regulatory region binding; transcription coactivator activity; transcription coregulator activity; protein serine/threonine kinase activity
Biological process: positive regulation of canonical NF-kappaB signal transduction; positive regulation of DNA-templated transcription; positive regulation of G2/M transition of mitotic cell cycle; positive regulation of transcription by RNA polymerase II; positive regulation of transcription elongation by RNA polymerase II; regulation of inflammatory response; regulation of transcription by RNA polymerase II; positive regulation of T-helper 17 cell lineage commitment; chromatin organization; regulation of DNA-templated transcription
Cellular component: chromosome; condensed nuclear chromosome; nucleoplasm; nucleus; chromatin
Genetic constraint (gnomAD): Loss-of-function variants: 15 observed, 120.82 expected, observed/expected ratio (o/e) 0.12, 90% interval 0.082 to 0.19. The synonymous counts are far from expectation, so gnomAD's model fits this gene poorly and the ratio says little. Missense variants: 1,372 observed, 1,667.5 expected, observed/expected ratio (o/e) 0.82, 90% interval 0.79 to 0.86. Synonymous variants: 795 observed, 649.08 expected, observed/expected ratio (o/e) 1.22, 90% interval 1.15 to 1.3.
Gene-disease validity (ClinGen):
ClinGen rates the evidence that BRD4 causes each of these diseases.
syndromic intellectual disability (autosomal dominant): Definitive. A intellectual disability that is part of a larger syndrome.
Cancer hallmarks: proliferative signalling (promotes); cell replicative immortality (promotes); escaping programmed cell death (promotes)
Homologues: Orthologues: chimpanzee BRD4 (100% identical), pig BRD4 (97% identical), guinea pig BRD4 (96% identical), mouse Brd4 (96% identical), tropical clawed frog cecr2 (11% identical), Caenorhabditis elegans baz-2 (7% identical), Drosophila melanogaster Acf (6% identical). Paralogues in human: BRDT (32% identical), BRD3 (32% identical), BRD2 (31% identical), CECR2 (16% identical), BPTF (13% identical), BAZ2B (11% identical), BAZ2A (10% identical), BAZ1A (9% identical), BAZ1B (8% identical), KAT2B (6% identical), KAT2A (5% identical).
Diseases named in the same sentence as BRD4 in open-access papers:
BRD4 is named in the same sentence as 374 diseases in open-access papers, as found by Europe PMC text mining. Sharing a sentence is not in itself a finding about the gene and the disease. The quoted sentences say what the papers report.
breast cancer (176 papers, 2012 to 2026). A primary or metastatic malignant neoplasm involving the breast. "BRD4, a transcriptional regulator that recognizes acetylated histones, is implicated in the pathogenesis and progression of various tumors, including breast cancer." (PMID 42239905, 2026). "A positive association (z score) was found between breast cancer BRD4 expression and clinical breast cancer stage (stages 3 and 4, P < 0.001)." (PMID 40762981, 2025). "Bromodomain-containing protein 4 (BRD4) regulates gene transcription and has been implicated in breast cancer progression by promoting cell proliferation and survival." (PMID 38474678, 2024). "In following, reactivation of macro-bound enhancers is associated with oncogenic programs in breast cancer and their repressive role is correlated with the activity of macroH2A2 as a negative regulator of BRD4 chromatin occupancy." (PMID 36823213, 2023). "The in vitro and in vivo disinclination of luminal breast cancer cells to AKT inhibitors is considerably mitigated by the pharmacological suppression of either BRD4/FOXO3A association or CDK6." (PMID 37626655, 2023). "Dysregulation of BRD4 has been implicated in a variety of human cancers, including acute myeloid leukemia and breast cancer." (PMID 36475791, 2022). "High expression of ZRF1 or BRD4 was also associated with poor survival of patients with breast cancer, colon cancer, Ewing sarcoma, glioma, melanoma, myeloma, or renal cancer." (PMID 34579723, 2021). "Tumoral BRD4 expression in breast cancer is significantly associated with T-bet+ TILs, clinicopathological features, and a poor disease-free survival in the absence of T-bet+ TILs." (PMID 30029633, 2018). "Their further study on 77 breast cancer cell lines reveals that BRD4 is a putative targeted option for luminal breast cancer and PIK3CA mutations probably determine the resistance to bromodomain and extra-terminal domain (BET)-inhibitors." (PMID 29753129, 2018). "Here we show that tumoral BRD4 expression is associated with T-bet+ TILs, relatively aggressive clinicopathological features, and a poor disease-free outcome in breast cancer." (PMID 30029633, 2018). "Pharmacological inhibition of either BRD4/FOXO3a association or CDK6 significantly overcomes the resistance of luminal breast cancer cells to AKT inhibitors in vitro and in vivo." (PMID 30518851, 2018). "In this prospectively accrued cohort of women with ANN breast cancer, we examined the relationship between BRD4 and T-bet+ TILs, and evaluated associations of BRD4 expression with Jagged1, clinicopathological features, and clinical outcomes." (PMID 30029633, 2018). "We find that cPRC1 complexes functionally associate with ERα and its pioneer factor FOXA1 in ER+ breast cancer cells, and with BRD4 in triple-negative breast cancer cells (TNBC)." (PMID 30139998, 2018). "Although recent elucidation of the diagnostic, prognostic and therapeutic value of BRD4 in lots of cancers, such as breast cancer, acute myeloid leukemia, and colorectal cancer, its role in non-small cell lung cancer (NSCLC) remains elusive." (PMID 26840017, 2016). "They provided the evidences that BRD4 long isoform reduced metastasis, however short isoform enhanced metastasis in breast cancer through interactions with the metastasis susceptibility protein RRP1B and SIPA1." (PMID 25603177, 2015). "Using a genetically engineered mouse model of aggressive breast cancer we demonstrated that Brd4 expression levels were associated with extracellular matrix genes, components of human breast cancer prognostic gene signatures." (PMID 24260471, 2013).
breast cancer (continued). "We will also discuss the association of two genes, Brd4 and Sipa1 (signal-induced proliferation-associated 1), with mammary tumor progression in both the mouse and the human." (PMID 22295248, 2012). "BRD4 functions as an inherited susceptibility gene for breast cancer progression and metastasis and regulates the transcription of select genes through epigenetic mechanisms." (PMID 22570792, 2012). "Recently, we have shown that the bromodomain-containing protein 4 or bromodomain 4 (Brd4) functions as an inherited susceptibility gene for breast cancer progression and metastasis." (PMID 22295248, 2012). "BRD4 dysfunction is associated with the tumorigenesis and progression of a variety of cancers, including acute myeloid leukemia, colon cancer, Burkitt's lymphoma, breast cancer, diffused large B-cell lymphoma, multiple myeloma, and ovarian cancer." (PMID 38130463, 2023). "Furthermore, Peli1 has been implicated in modulating the tolerance to JQ1 targeting BRD4 in breast cancer." (PMID 38179042, 2023). "Importantly, BRCA1 deficiency further sensitizes breast cancer cells to BRD4 inhibition, as this inhibition suppresses MYC expression and transcription and thereby induces oxidative stress and DNA damage." (PMID 36139513, 2022). "Furthermore, recent studies in breast cancer and acute myeloid leukaemia reported opposite oncogenic functions of the short and long BRD4 isoform underlining the importance to distinguish between these isoforms." (PMID 35182012, 2022). "Importantly, PIK3CA mutations confer resistance to BRD4 inhibition in breast cancer, which can be reversed using PIK3CA-specific or mTOR inhibitors." (PMID 36139513, 2022). "Because we observed an increase in H3K4me3 associated with the HOTAIR‐N promoter, we speculated that BRD4 mediated induction of HOTAIR in lrECM 3D culture of Claudin‐low breast cancer cells." (PMID 28846832, 2017). "Furthermore, Brd4 is believed to be an inherited susceptibility gene for breast cancer progression and metastasis." (PMID 24759736, 2014). "Our recent data suggest that the metastasis susceptibility gene BRD4 appears to play a significant role in establishing transcriptional programs that predict breast cancer outcome via a balance between the tumor- and metastasis-suppressive long isoform and the metastasis-promoting short isoform." (PMID 22295248, 2012). "The BRD4 portion encoded by this transcript (in the estimated chimeric protein) has the same length and structure of a shorter isoform of the protein (BRD4-S) previously shown to be implicated in breast cancer growth and metastasis, potentially mimicking BRD4-S pro-oncogenic activity." (PMID 38500181, 2024). "In the context of breast cancer brain metastasis, we also found BRD4 silencing caused downregulation of two downstream target molecules, Shh and Gli, while BRD4 overexpression improved their expression, suggesting that BRD4 may promote MMP9 expression through SHH signaling pathway in 231-BR cells." (PMID 34421353, 2021). "Hence, the BRD4-c-Myc axis not only drives tumor development, but also serves as a source of promising targets for mitigating 8q24 amplification-associated malignancy in breast cancer." (PMID 33006750, 2020). "We find that BRD4 is the key discriminant of tissue-specific enhancers, showing that it is more powerful than AR binding information to capture PC specific risk loci, and can be used with similar effect in breast cancer (BC) and applied to other diseases such as schizophrenia." (PMID 28359301, 2017). "In recent years, several studies have demonstrated that BRD4 plays a key role in cell proliferation, survival and metastasis of breast cancer, and can be used as an emerging therapeutic target for down-regulating TNBC." (PMID 41525248, 2026). "DBET6, a PROTAC-based BRD4 degrader, effectively and continuously degrades BRD4 protein, thereby exerting potent antitumor effects, such as breast cancer, lung cancer, etc." (PMID 41525248, 2026).
breast cancer (continued). "The antitumor effect of a PROTAC-targeted BRD4 degrader, alone or in combination with fulvestrant, was evaluated in breast cancer cells." (PMID 42239905, 2026). "A PROTAC-targeted BRD4 degrader significantly enhanced the antitumor efficacy of fulvestrant in breast cancer cells." (PMID 42239905, 2026). "In summary, Exo-BSA@dBET6 regulate a series of apoptosis-related proteins and breast cancer-related signaling pathways by down-regulating BRD4 protein, and finally play an anti-TNBC tumor role." (PMID 41525248, 2026). "We have previously shown that SETD6 specifically methylates BRD4 at K99 in a breast cancer cellular model, which in turn regulates the transcription of genes that control mRNA translation." (PMID 40809945, 2025). "In breast cancer cells, BRD4 methylation specifically determines the recruitment of the TF E2F1 to selected target genes." (PMID 40809945, 2025). "The authors show that the combination of HDACi with JAK1 or BRD4 inhibition sensitises breast cancer cells to HDACi, and suggest this combination treatment strategy for the treatment of breast cancer." (PMID 40011240, 2025). "Our previous studies in ER-positive breast cancer also revealed that ARV-825 treatment successfully downregulated BRD4 and c-Myc expression and prolonged growth arrest while further sensitizing breast cancer cells to palbociclib + fulvestrant treatment." (PMID 40649963, 2025). "The TIMER2 (tumor immune estimation resource) and TIDE tools were used to explore the association between BRD4 gene expression and MDSC populations in tumors from human breast cancer patients." (PMID 40762981, 2025). "In breast cancer cells, researchers unexpectedly discovered that BRD4 interacts with the LSD1/NuRD complex to form an inhibitory complex, which co - localizes on super - enhancers." (PMID 39838405, 2025). "This revealed recurrent focal deletions (<100 kbp) in BRD4 in 16 tumors, including 4 breast cancers, 7 ovarian, 3 endometrial and 2 colorectal cancers." (PMID 40112818, 2025). "In breast cancer, BRD4 inhibitor combined with radiotherapy reduced PD-L1 and HIF-1α expression, remodeled myeloid cells toward an immunostimulatory phenotype, and expanded CD4+/CD8+ T cell populations." (PMID 41583469, 2025). "When normalized for locus-specific copy number, we identified significantly decreased copy-number-adjusted BRD4 expression of BRD4-L and both isoforms of BRD4-S in breast cancer tumors with BRD4 focal deletions." (PMID 40112818, 2025). "Co-inhibition of BET and CDK4/6 further destabilizes BRD4 and impairs homologous recombination in breast cancer." (PMID 41583469, 2025). "A recent study found an increase of 6,197 BRD4-binding sites in ARID1A knockout breast cancer cells, indicating a significant increase in BRD4 chromatin binding activity." (PMID 41049615, 2025). "In human breast cancer cell lines, knockdown or small-molecule inhibition of BRD4 reduces migration and invasion phenotypes." (PMID 38935814, 2024). "The antiproliferation activities of different compounds were positively correlated with their BRD4 degradation abilities, suggesting that BRD4 degradation contributed substantially to the antiproliferation activity of breast cancer." (PMID 38768083, 2024). "To evaluate the efficacy of HL435 in depleting BRD4, we conducted a concentration-dependent study in human breast cancer cell lines." (PMID 38768083, 2024). "Bromodomain-containing protein 4 (BRD4), a chromosome-binding protein associated with gene expression, plays a key role in the pathological process of breast cancer." (PMID 38421832, 2024). "In this study, we used a unique synthetic lethal drug combination targeting BRD4 and the proteasome to induce ferroptosis in basal‐like breast cancer." (PMID 38441406, 2024). "Further research into the role of BRD4 inhibitors in inhibiting metastasis in ovarian cancer, as shown in breast cancer, would help treat ovarian cancer." (PMID 38473320, 2024).